HSP90AA1 (heat shock protein 90 alpha family class A member 1)
Diseases named in the same sentence as HSP90AA1 in open-access papers (continued):
Sharing a sentence is not in itself a finding about the gene and the disease.
tumor (continued). "The expression levels of CCND1, VEGFA, AURKB, HDAC1, HSP90AA1, and HSP90AB1 were positively correlated with immune cell infiltration levels, whereas the expression levels of SIRT2 and CASP9 were negatively correlated with the tumor purity of BRCA." (PMID 35845599, 2022). "Taken together, the result supported the anti-tumor action of extracellular Hsp90ab1, and not Hsp90aa1, in regulating Lrp5, Runx2, TGFβ, and IL27 in tumor cells." (PMID 34830748, 2021). "ZNRD1-AS1 knockdown suppressed tumor growth and pulmonary metastasis in a nude mouse model ZNRD1-AS1 can bind to miR-9-5p and ZNRD1-AS1 knockdown can decrease the protein level of heat shock protein 90 alpha family class A member 1 (HSP90AA1), which is the target of miR-9-5p." (PMID 34226297, 2021). "Fold change in HSP90AA1 (by 9.4-fold) but not HSPA1 expression was significantly greater in neoplasms located in the rectum as compared to right/left colon." (PMID 34827586, 2021). "It indicated that HSP90AA1 might act as a key molecule, through protein interaction and targeted miRNAs, for SFN to function as a tumor suppressor." (PMID 33491737, 2021). "From the ginsenoside-target-pathway network, we observed that EGFR, ESR1, ESR2, HSP90AA1, and RELA are all critical genes that we should focus on, which may reveal the anti-tumor mechanism of G-Rk1 and G-Rg5." (PMID 34199025, 2021). "In particular, AHA1, but not Hsp90aa1 and Hsp90ab, was closely associated with the TNM stage, LN stage, and tumor metastasis (p = 0.035, p = 0.012, and p = 0.0003, respectively)." (PMID 34620942, 2021). "Examples of anti-tumor activity of secreted HSPs include HSPA1A and HSP90AA1." (PMID 28468249, 2017). "Taken together, the combination of a HSP90AA1 inhibitor and a MTOR inhibitor not only activates autophagy, leading to KIT downregulation, but also likely exerts anti-angiogenic effects that to contribute to tumor growth inhibition in vivo in our study." (PMID 25375091, 2014). "Network pharmacology prioritized STAT3, HSP90AA1, CASP3, CASP8, and SRC as core therapeutic targets, with molecular docking confirming stable interactions between these two metabolites and targets, highlighting their potential in managing infections, neoplasms, and metabolic disorders." (PMID 41295287, 2025). "The KEGG signaling pathway enrichment results also indicated that isoscopoletin might play an anti-tumor role by affecting the core targets of glycolysis pathway, such as GPD2, GPI, Hsp90AA1 and PGK2, which were the intersection of most glycolysis-related pathways." (PMID 39509399, 2024). "The expression levels of mRNA and proteins of TSR1, WDR46, HSP90AA1, and NOP56 in DLBCL were significantly higher than those in normal tissues, suggesting that these four hub genes can be activated and can upregulate the expression of mRNA during tumor development." (PMID 35263200, 2022). "Some studies found that, in tumor biopsies, the absence of HSP90AA1 may serve as a biomarker of favorable outcomes." (PMID 34194515, 2021). "In addition, knockdown of HSP90AA1 in P3 cells decreased in vitro sphere-forming capacity and reduced tumor-initiating property when transplanted into NOD/SCID mice, indicating that HSP90A is important for maintenance of CSC-like properties in immune-edited P3 tumor cells." (PMID 31992715, 2020). "Other studies also found that, in tumor biopsies, the absence of HSP90AA1 may serves as a biomarker for favorable outcomes." (PMID 30153855, 2018). "However, HSP90AA1 exhibited an up–down expression pattern along the trajectory, while TAGLN2 remained stable during early differentiation and markedly increased at the later stages, indicating potential roles in fibroblast maturation and tumor microenvironment remodeling." (PMID 40299459, 2025). "The results showed that the expression of HSP90AA1, HSP90AB1, and TRAP1 was positively correlated to the tumor purity, while that of HSP90B1 was not." (PMID 33145341, 2020).
infection (24 papers, 2017 to 2025). The state of being infected such as from the introduction of a foreign agent such as serum, vaccine, antigenic substance or organism. "HSP90AA1 is a critical molecular chaperone that is highly conserved in evolution and expressed under the stimulatory circumstances of trauma, infection, and tumors." (PMID 38685981, 2024). "Seven genes were observed to be involved in both infections of three coronaviruses and two neurodegenerative diseases, including the HSP90AA1, ALDH2, CAV1, COMT, MTOR, IGF2R and HSPA1A." (PMID 37015947, 2023). "HSP90AA1 is highly expressed under the stimulatory circumstances of trauma, infection, and tumors and plays an essential role in DNA damage regulation, cell cycle regulation, gene expression and carcinogenesis." (PMID 36532769, 2022). "During infection control, HSP90AA1 induces autophagy by interacting with the AKT-MTOR pathway after recognizing the virus." (PMID 36353282, 2022). "We observed transient deregulation of the stress-responsive HSP gene HSP90AA1, in both the “slow-motion” infection model, H1299 cells, and in Calu-3 cells (4 hpi), and in subsets of epithelial cells in patient samples." (PMID 33585804, 2021). "Collectively, the results demonstrate that HSP90AA1 distributed on the cell membrane plays a critical role in the entry and infection of IAV." (PMID 33117314, 2020). "A previous study demonstrated that the degradation of IBDV particles in autophagic vacuoles and the binding of viral protein VP2 to HSP90AA1 activate autophagy by the AKT-MTOR pathway in the early stage of infection." (PMID 32967959, 2020). "MA10 infection induced seven additional down-regulated (Hsp90aa1, Tcf7l2, Gnas, Sparcl1, Ywhag, Cpe, Sparc) and four upregulated DEGs (Ppp1r1b, Penk, Arpp21, Pcp4), whereas Aβ pathology resulted in five down-regulated (Cplx1, Syp, Meg3, Snhg11, Penk) and one upregulated DEG (Psen1)." (PMID 41497643, 2025). "For example, the HSP90AA1 took part in infections of 13 viruses." (PMID 37015947, 2023). "Pretreatment of IAV with recombinant HSP90AA1 protein also greatly decreased infection." (PMID 33117314, 2020). "It is reported that a direct connection between HSP90AA1 and the AKT-mTOR pathway triggers autophagy, which is a critical step for controlling infection." (PMID 40727105, 2025). "An increase in productive infection was detected after knockdown of FLNA, HMGB3, PTBP1, HSP90AA1, and KIF2C (green bars)." (PMID 34194479, 2021). "HSP90AA1, a pathogen receptor, induces autophagy via an AKT–MTOR-dependent pathway during early infection." (PMID 29368634, 2018). "Members of the heat shock protein family such as HSP90AA1 and HSP90AB1 may support viral replication by modulating protein folding and stability during infection." (PMID 41404797, 2025). "Moreover, The HA protein bound with HSP90AA1 to inhibit the AKT/mTOR signalling pathway and inducing complete autophagy to degrade innate immunity factors in early infection." (PMID 34967267, 2022). "Under infection, wIRA radiation could restore HSPA1A levels to control levels and alleviate HSP90AA1 increases in keratinocytes, which might have contributed to the slightly improved survival of wIRA-treated, infected keratinocytes." (PMID 34944618, 2021). "Under infection, wIRA radiation could restore HSPA1A transcription to control levels and alleviate HSP90AA1 increases in keratinocytes." (PMID 34944618, 2021). "Notably, the HSP90AA1 and HSPA1A took part in infections of 16 and 12 viruses, respectively." (PMID 37015947, 2023).
neurodegenerative disease (7 papers, 2013 to 2024). A disorder of the central nervous system characterized by gradual and progressive loss of neural tissue and neurologic function. "HSPs, including HSP90AA1, HSPA8 and DNAJB1 (all upregulated in the presence of P2RY6 antagonist) are key players in chaperone-mediated autophagy (CMA), a form of autophagy that is impaired in aging and neurodegenerative diseases." (PMID 36203578, 2022). "Additionally, the elevated HSP90AA1 and P2RX7 levels could in turn lead to tau hyperphosphorylation and neuroinflammation, two critical contributors to this neurodegenerative disease." (PMID 38360834, 2024).
adenocarcinoma (4 papers, 2021 to 2024). A common cancer characterized by the presence of malignant glandular cells. "Thus, HSP90AA1 increases the potential for our ICD-related progonstic model to generalize well to different adenocarcinoma samples." (PMID 37587188, 2023). "Likewise, fold change in HSP90AA1 expression tended to be greater in patients with high grade polyps or adenocarcinomas due to significantly lower expression in normal polyp-adjacent mucosa." (PMID 34827586, 2021).
cardiovascular disease (4 papers, 2011 to 2024). "HSP90AA1 (also known as HSP90A), a therapeutic target for cardiovascular disease and cardiac ageing, has been reported to mediate angiogenesis by direct binding to semi-synthetic triterpenoids, and it was found to be strongly related to the severity degree of COVID-19 disease." (PMID 37047484, 2023). "Of particular interest was the observation that only a few of the most significantly up/downregulated proteins such as the superoxide dismutase (SOD2), HSP90AA1 or GOT1, could be allotted a cardiac-related function, or may have been implicated in cardiovascular disease thus far." (PMID 27711126, 2016).
hematologic malignancies (2 papers, 2018 to 2020). "Recent research has shown the gene HSP90AA1 is related to hematological malignancies." (PMID 30255785, 2018).
metabolic disorders (2 papers, 2025). "GM dysbiosis and inflammation also induce epigenetic alterations in cytokine genes, such as IL-1β, IL-6, TNF-α, NF-kB, BTLA, IL-18R1, TGF-β, P13k/Akt1, Ctnnb1, and Hsp90aa1, as well as DNMTs, HDACs, and DAT1 associated with the development and progression of metabolic disorders and/or NPDs." (PMID 41228440, 2025).
infectious disease (1 paper, 2014). A disorder directly resulting from the presence and activity of a microbial, viral, or parasitic agent in humans. "Previous studies showed that HSP90AA1 played an important role in infectious disease by interacting with various bacterial and viral proteins." (PMID 24809979, 2014).
HSP90AA1 also shares sentences with these, for which no sentence is quoted: malaria (4 papers); type 2 diabetes (4); Hyperglycemia (3); myeloma (3); autoimmune disease (2); Azoospermia (2); endometrial cancer (2); gout (2); hepatitis B (2); hypoglycaemia (2); immune disease (2); inflammatory bowel disease (2); insomnia (2); mesothelioma (2); neuroblastoma (2); osteoporosis (2); squamous carcinoma (2); testicular germ cell tumor (2); uveal melanoma (2); varicocele (2); acute monocytic leukemia (1); acute myocardial infarction (1); adenolymphoma (1); adrenal cortex carcinoma (1); adrenocortical adenoma (1); alcoholic hepatitis (1); allergic disease (1); amyloid (1); anaplastic large cell lymphoma (1); ankylosing spondylitis (1).
A further 58 diseases each share a sentence with HSP90AA1 in 1 paper.